CCL2 (C-C motif chemokine ligand 2)
Diseases named in the same sentence as CCL2 in open-access papers (continued):
Sharing a sentence is not in itself a finding about the gene and the disease.
asthma (155 papers, 2004 to 2026). "In VISTA KO mice, elevated levels of inflammatory cytokines and chemokines such as Ccl2 (MCP1) are observed in the lung, which is associated with the development of experimental asthma." (PMID 32856125, 2020). "Several asthma susceptibility genes have been identified by the genome-wide association studies, of which the monocyte chemoattractant protein-1 (MCP-1, also termed as CCL2) has been extensively studied (4, –6)." (PMID 31664304, 2019). "Previous studies demonstrated that CCL2 was implicated in HRV induced airway hyper-responsiveness as a mechanism underlying asthma exacerbation." (PMID 28558071, 2017). "The association of HIF-1α and CCL2 levels was also measured in endobronchial biopsies and bronchial fluid of asthma patients after challenge." (PMID 22823210, 2012). "In addition, CCL2 is involved in the polarization of Th2 cells and therefore is associated with the pathogenesis of allergic inflammatory diseases, such as asthma." (PMID 26075216, 2015). "In the asthma model induced by ovalbumin, the anti-inflammatory role of chemerin was not linked to a direct effect on the recruitment of pro-inflammatory DCs but to an interaction with lung epithelial cells, decreasing their secretion of CCL2, another chemoattractant agent." (PMID 38247862, 2024). "This was accompanied by reduced levels of CXCL1, CCL11, and CCL2 chemokines and the consequent reduced inflammation in lungs and airways which contributed to the improvement of pulmonary mechanics, the main cause of asthma complications and worsening of life quality of patients with asthma." (PMID 33123138, 2020). "Epithelium-derived factors (TSLP, IL-33, CCL2) are also known to induce DC migration and maturation, especially of moDCs in severe asthma." (PMID 39244793, 2024). "CCL2 expression has been found to be increased in asthma patient BAL compared to healthy controls, suggesting enhanced monocyte recruitment in asthma." (PMID 37445635, 2023). "More unexpected was the apparent participation of monocytes/macrophages in asthma conducted possibly by production of MCP-1/CCL2, IL-8 homologues, and recruitment of monocytes into the lungs." (PMID 37790940, 2023). "Collectively, these studies suggest that CCL2 production by lung macrophages contributes to monocyte recruitment and macrophage activation in asthma." (PMID 37445635, 2023). "The airway epithelium expresses CCL2, CCL3, CCL4, CCL5, CCL11, and CXCL5, which are associated with asthma." (PMID 35743888, 2022). "The pro-inflammatory cytokines IL-1B and IL-6, on the other hand, are reduced in Sarcoidosis exosomes, whereas asthma treatment encourages monocytes to produce pro-inflammatory cytokines and CCL2." (PMID 35928365, 2022). "CDH12 expression is positively modulated by the chemotactic factor CCL2,53, 54 whose levels increases in blood and airway smooth muscle from asthma patients compared to healthy controls." (PMID 35754128, 2022). "BSMCs treated with polyI:C, had a significant increase in mRNA expression of IL-6, IFN-β1, CCL2 compared to untreated cells and this effect was observed to a higher extent in asthma and COPD BSMCs (p < 0.05)." (PMID 34512638, 2021). "Downregulation of CCL2 by ADPN potentially prevents this complication of asthma in human primary bronchial epithelial extract." (PMID 34445677, 2021). "IL-5 and IL-13 showed strong correlations with AHR and CCL2 (MCP-1) in asthma severity and fast lung function decline." (PMID 33806085, 2021). "Analysis of the miRNA–target gene network noted an overlapping KEGG signaling pathway, hsa04060: cytokine-cytokine receptor interaction, in which the gene CCL2, directly related to asthma, was involved." (PMID 34525985, 2021). "To ascertain the mechanisms underlying GLCCI1-mediated regulation of the effects of GCs on chemokines, we began by assessing asthma-related pro-inflammatory chemokines (CCL2, CCL3, CCL4, and CCL7) in lung tissues by RT-PCR." (PMID 34504850, 2021).
asthma (continued). "The potently chemotactic chemokine CCL2 was induced by exosomes from a subgroup of patients, and in a blocking assay the exosome-induced CCL2 was reduced for 13 out of 19 patients by the asthma drug Montelukast, a cysteinyl leukotriene receptor antagonist." (PMID 32948789, 2020). "Our RNA-Seq results showing that CCL2, CCL13, and IL8 mRNA levels were elevated in fatal asthma-derived ASM are consistent with these previous studies showing elevated levels in ASM (for CCL2) and other tissues." (PMID 26207385, 2015). "Sputum IL-6 and CCL2 levels were significantly higher in subjects with COPD than in subjects with asthma, with ROC AUCs of 0.86 (95% CI, 0.81-0.92; P < .0001) and 0.69 (0.61-0.77; P < .0001), respectively." (PMID 25129678, 2015). "CCL2 has also been found to promote mast cell recruitment and Th17 cell migration to the lung in mouse models of asthma." (PMID 26207385, 2015). "In conclusion, these observations confirm previous findings of increased CCL2 levels in asthma and suggest that ASM-derived CCL2-mediated activation of CCR2 promotes FC migration." (PMID 24931417, 2014). "Together, these findings implicate a role for CCL2 in FC trafficking to the ASM in asthma and possibly to consequent ASM hyperplasia and airway remodelling." (PMID 24931417, 2014). "We provide evidence for CCR2 expression on human FCs and a role for CCL2 in modulating FC migration towards the ASM bundle in asthma." (PMID 24931417, 2014). "Neutralization of CCL2 in allergen-induced models of asthma has been shown to decrease AHR, inflammation, and macrophage infiltration." (PMID 24499286, 2014). "Some highly significant genes in the microarray analysis also relevant to asthma (Ccl2, Ccl11, Ccl24 and Cxcl5) were further confirmed by quantitative PCR." (PMID 25318534, 2014). "IL1RA (p = 0.055), IL-17 (p = 0.072) and CCL2 (p = 0.083) demonstrated a tendency to a significantly higher concentration in smokers with asthma." (PMID 23951170, 2013). "The results lead us to suggest that Abl expression in smooth muscle does not modulate inflammatory cell infiltration and production of IL-13 and CCL2 in asthma." (PMID 24112389, 2013). "We found that the following chemokines were significantly up-regulated in the serum in asthma compared to healthy subjects CCL2, CCL4, CCL11 and CCL13 (p < 0.05)." (PMID 19602238, 2009). "Other components and pathways that are positively associated with CCL2 granule in IPF patients include azurophil granule and several immune-related pathways, such as allograft rejection, asthma, graft-versus-host disease and viral protein interaction with cytokine and cytokine receptor." (PMID 39753882, 2025). "In asthma, CCL2 is often overexpressed, and blocking CCL2 or its receptor alleviates symptoms." (PMID 41169790, 2025). "CCL2 levels are increased in the blood of asthmatic patients compared with healthy controls, contributing to fibrocyte migration and to airway smooth muscle hyperplasia development in asthma." (PMID 39273372, 2024). "The overexpression of CCL2 is a trigger to respond to allergies and asthma." (PMID 35678682, 2022). "Seven hypermethylated (CCL11, TNF, IL5, CCL2, CXCL1, CCL8, IL17RB) mRNAs (>twofold compared with control) were finally selected, as their mRNAs have been clearly reported as being associated with asthma." (PMID 36250525, 2022). "In a regulatory network directly related to asthma, the KEGG signaling pathway hsa04060:cyclokine-cyclokine receptor interaction was found, in which the CCL2 gene, directly related to asthma, is involved, and this gene is targeted by eight asthma related miRNAs." (PMID 34525985, 2021). "CCL2 is closely involved in the inflammatory response in children with asthma." (PMID 34525985, 2021). "We speculate that IL2RG and CCL4, which are also involved in this pathway, might be critical genes related to childhood specific asthma, and together with CCL2 play a role in this disease." (PMID 34525985, 2021).
asthma (continued). "In the miRNA−target gene regulatory network directly related to asthma, an overlapping KEGG pathway, hsa04060: cytokine−cytokine receptor interaction, was noted, in which the CCL2 gene directly related to asthma is involved, and the gene is targeted by 8 asthma related miRNAs." (PMID 34525985, 2021). "In addition, bone-marrow-derived macrophages isolated from Lyz2cre:Bmal1flox animals and stimulated with LPS ex vivo exhibited a higher expression of the asthma-relevant chemokines CCL2, CXCL10, as well as the asthma-associated mannose receptor." (PMID 31931006, 2020). "Further, for 22 h stimulated PBMCs the levels of CCL2 could be reduced in 13 out of 19 patient exosome stimulations using Montelukast, a commonly used asthma drug." (PMID 32948789, 2020). "Interestingly, both p38α MAPK and IKK-2 activities are elevated in severe asthma, as are a number of H3-Pser10-regulated genes including IL-6, CCL-2 and CXCL-8." (PMID 25905622, 2015). "Our findings are consistent with a body of evidence supporting a role for CCL2 in asthma." (PMID 24931417, 2014). "To determine the role of Abl in smooth muscle in the production of cytokine and chemokine, we evaluated the level of IL-13 and CCL2 (representative cytokine and chemokine in asthma pathology) in the BALF in lungs of naïve and OVA-treated Abl-lox and Ablsm−/− mice." (PMID 24112389, 2013). "In the type 2-low asthma model, Sema3E-deficient mice exhibited increased tissue resistance and elastance, accompanied by elevated levels of neutrophils, dendritic cells, CD4 + T cells, and pro-inflammatory cytokines such as IL-17, TNF, IL-1β, CXCL-8, and MCP-1/CCL2." (PMID 40512736, 2025). "However, a large dataset, focused on a healthy cohort, allowed us to identify statistically significant differences in the expression of CCL20, CCL2 and IL-10, all of which are important during rhinovirus infection and virally induced asthma exacerbations, after exposure with HRV16 and HRV1A." (PMID 24736642, 2014). "In addition, we generated conditional knockout mice in which Abl expression in smooth muscle was disrupted, and then evaluated the effects of Abl conditional knockout on airway resistance, smooth muscle mass, cell proliferation, IL-13 and CCL2 in the mouse model of asthma." (PMID 24112389, 2013). "CCL2 may have a significant role in the pathogenesis of asthma because of its ability to recruit eosinophils and monocytes, activate basophils and mast cells and induce the release of leukotriene C4 into the airway, all of which contribute to airway hyperresponsiveness." (PMID 22823210, 2012). "Conversely, CCR2 facilitates CD11b+ DC recruitment to inflamed lungs through interactions with CCL2 and CCL8, both of which are highly expressed in asthma." (PMID 40405264, 2025). "Chemokines such as CXCL8 (IL-8), CCL2 (MCP-1), and CCL5 (RANTES) are significantly upregulated during asthma-related lung inflammation." (PMID 39902079, 2024). "In asthma, MIF induces CCl2, CXCR2, and CXCR4 expression through the ERK / MAPK / P38 / Rho A GTPase pathway." (PMID 37422662, 2023). "The cytokine production of IL-6, CCL-2, and IL-12p40 in the lungs and BAL significantly increased after viral challenge in both the naïve-infection and asthma-infection groups." (PMID 37424011, 2023). "The most influential nodes (Fn1, Igf1, Ccl2, C3, Timp1, Cxcl12, Ccl4, Ccr2, Spp1, C3ar1, Cat, Cyp2e1, Muc5ac, Muc5b) were selected for further validation in the OVA-induced asthma and post-asthmatic fibrosis murine model." (PMID 35625754, 2022). "The levels of CCL2, CCL3, and CCL5 in the BALF and CCL11 in plasma were significantly higher in asthma patients than in control subjects." (PMID 35743888, 2022). "For the inflammatory cytokines in the lung, the contents of TNF-α, TNFR2, CXCL-9, CCL-12, CCL-9, CCL-2, and CCL-5 in the asthma model group were higher than those in the control group, while the contents of GM-CSF and IL-1α were decreased." (PMID 35600943, 2022).
asthma (continued). "Our findings indicated that pro-inflammatory and pro-fibrotic mediators are increased at the baseline in BSMCs from both asthma and COPD, and that TLR3 agonist polyI:C, significantly upregulated IL-6, IFN-β1, CCL2, FN1 and COL1A1 expressions in BSMCs." (PMID 34512638, 2021). "High levels of CCL2 and CCL5 in the BALF along with increased IL-5 in patients with asthma induce eosinophil infiltration and activation." (PMID 33806085, 2021). "Here we report the mRNA expression and protein levels of pro-inflammatory and pro-fibrotic markers (IL-6, IFN-β1, CCL2/MCP-1, fibronectin 1 and type I collagen) among BSMCs groups: asthma, COPD, and healthy controls." (PMID 34512638, 2021). "In asthma, ASM produces various cytokines, such as monocyte chemoattractant protein 1 (CCL2), which, in turn, promotes fibrocyte migration and ASM hyperplasia in asthma." (PMID 34445677, 2021). "il-10, il-4, il-13, il-17a, il-2, tlr4, tlr9, ccl2, csf2, and vegfα are top 10 hub nodes in the PPI network, so we inquired the expression profiles of these genes in asthma from the GEO database." (PMID 33133221, 2020). "Higher relative abundance of these bacteria is furthermore associated with an airway immune profile dominated by reduced TNF-α and IL-1β and increased CCL2 and CCL17, which itself is an independent predictor for asthma." (PMID 31676759, 2019). "This asthma-associated composition furthermore correlated with lower levels of topical pro-inflammatory airway immune mediators (IL-1β and TNF-α), which may characterize an inefficient anti-bacterial response, and higher levels of monocyte and T-cell recruiting chemoattractants (CCL2 and CCL17)." (PMID 31676759, 2019). "Follow-up qPCR and individual analyte ELISA experiments were conducted for four cytokines (i.e. CCL2, CCL13, CXCL12, IL8) to measure TNFα-induced changes by asthma status and vitamin D treatment." (PMID 26207385, 2015). "At baseline, CCL2 and CXCL12 were secreted differently from fatal asthma and non-asthma derived ASM in directions consistent with RNA-Seq results, but only those of CXCL12 were statistically significant." (PMID 26207385, 2015). "The CCL2, CCL13, CXCL12, and IL8 cytokine genes selected for experimental follow-up are known to be involved in asthma related processes." (PMID 26207385, 2015). "We chose to focus our functional studies on four cytokines that were differentially expressed between fatal asthma- and non-asthma-derived ASM and were also modified by vitamin D treatment in fatal asthma-derived ASM (i.e., CCL2, CCL13, CXCL12, IL8)." (PMID 26207385, 2015). "The sputum inflammatory mediator profiles were distinct with increased TH2 (IL-5, IL-13, and CCL26) and TH1 mediators (CXCL10 and 11) in severe asthma compared with COPD and increased IL-6, CCL2, CCL3, and CCL4 in COPD compared with severe asthma." (PMID 25129678, 2015). "Differential activation of signaling pathways led to changes in the production of the asthma-relevant cytokines CCL20, CCL2, and IL-10." (PMID 24736642, 2014). "We report here for the first time that constitutive release of CCL2 by primary ASM is increased in asthma, that ASM-derived CCL2 promotes migration of FCs and that increased sputum CCL2 is associated with bronchial wall thickening." (PMID 24931417, 2014). "Airway smooth muscle-derived CCL2 mediates FC migration and potentially contributes to the development of ASM hyperplasia in asthma." (PMID 24931417, 2014). "The levels of interferon‐γ (IFN‐γ), tumor necrosis factor‐a (TNF‐α), chemokine CCL22 (CCL22), interleukin 12 (IL‐12), chemokine CCL4 (CCL4), chemokine CCL2 (CCL2), and chemokine CCL13 (CCL13)were significantly higher in the acute asthma group than in the stable asthma group." (PMID 39508721, 2024).
asthma (continued). "The serum levels of TNF‐α (p = 0.025), IFN‐γ (p = 0.011), CCL22 (p = 0.022), IL‐12p70 (p = 0.021), CXCL10 (p = 0.028), CCL2 (p = 0.028), CCL13 (p = 0.024), IL‐4 (p = 0.026), IL‐13 (p = 0.024), and CCL11 (p = 0.028) were found to be downregulated in stable asthma when compared to acute asthma." (PMID 39508721, 2024). "Additionally, we examined the levels of inflammatory cytokines in sputum and found that IL‐5, IL‐6, IL‐8, TNF‐α, IFN‐γ, CCL17, CCL22, CXCL10, CCL4, CCL2, IL‐4, IL‐13, and CCL26 were significantly lower in stable asthma than in acute asthma." (PMID 39508721, 2024). "In addition, the contents of TNF-α, TNFR2, CXCL-9, CCL-12, CCL-9, CCL-2, and CCL-5 in the asthma model group were higher than those in the control group, while the contents of GM-CSF and IL-1α were decreased." (PMID 35600943, 2022). "In T2-low asthma, macrophages recruitment is also driven by the epithelial release of CCL2 and CCL3, while in obesity-related asthma, leptin activates airway epithelial cells and induces the production of cytokines such as IL-8, further contributing to neutrophil recruitment." (PMID 35456002, 2022). "Additionally, MCP-1, a CC chemokine also named as chemokine (C–C motif) ligand 2 (CCL2), is an important inflammatory molecule in the airway epithelium in asthma." (PMID 31073274, 2019). "Cytokines including interleukin 4 (IL-4), interleukin 5 (IL-5), IL-6, IL-8, interleukin 10 (IL-10), monocyte chemoattractant protein (MCP)-1/CCL2, and thymus and activation-regulated chemokine (TARC)/CCL17 trigger secondary inflammatory events, aggravating asthma pathogenesis." (PMID 29755573, 2018). "Based on our results, CCL2, CXCL12, and IL8 may have correlated mRNA and protein secretion levels that differ between fatal asthma- and non-asthma-derived ASM, but the difference in IL8 may only be noticeable with TNFα induction due to its low baseline levels." (PMID 26207385, 2015). "A previous study found that CCL2 (aka MCP1) concentration was elevated in primary ASM supernatant and blood of asthma patients, its sputum levels were increased in asthma patients with bronchial wall thickening, and chemotaxis assays suggested that it mediates fibrocyte migration toward ASM." (PMID 26207385, 2015). "In the present work, AT-RvD1 significantly reduced CCL2 and CXCL-8 production in bronchial epithelial cells when compared to cells stimulated with IL-4, demonstrating the potential to reduce both neutrophilic and eosinophilic inflammation in asthma." (PMID 26075216, 2015). "In addition, CCL2 production by epithelial cells and macrophages has been reported to contribute to rhinovirus-induced airway hyperresponsiveness and inflammation in a mouse model of allergic airways disease and may play a role in rhinovirus-induced asthma exacerbations." (PMID 24204835, 2013). "In asthma patients, the levels of HIF-1α and CCL2 increased after challenge with the allergen." (PMID 22823210, 2012). "CCL2, which we detected in BAL, is a chemoattractant for monocytes and basophils while CCL24, also known as eotaxin-2, recruits eosinophils and basophils, is elevated in some forms of asthma and functions to induce inflammation after bronchial allergen challenge." (PMID 40725026, 2025). "Concurrently, Sema3E KO mice that were subjected to the type-2 low asthma model demonstrated an elevated presence of pulmonary neutrophils, dendritic cells, CD4 T cells, as well as increased levels of IL-17, TNF, IL-1β, CXCL-8, and MCP-1/CCL2 in comparison to their WT counterparts." (PMID 40512736, 2025). "However, some trials, like those involving CCR1/AZD4818 for COPD, CCR3/GSK766994 for asthma, and CCL2/Carlumab for IPF, have shown no efficacy." (PMID 39768150, 2024). "Monocyte chemotactic protein 1 (MCP-1) or CCL2 is a potent chemoattractant of macrophages and monocytes and due to their ability to recruit eosinophils, monocytes, activating mast cells and basophils, they may play significant role in asthma pathogenesis." (PMID 37316684, 2023).